PDE8B (phosphodiesterase 8B)
Description:
Hydrolyzes the second messenger cAMP, which is a key regulator of many important physiological processes. May be involved in specific signaling in the thyroid gland.
Synonyms: ADSD; PPNAD3
Tractability: Small molecule: an approved drug acts on it; a high-quality ligand is known; it belongs to a druggable protein family. PROTAC: ubiquitination databases record sites on it; a small molecule that binds it is known.
Target class: Phosphodiesterase; Phosphodiesterase 8B; Enzyme; Phosphodiesterase 8
Gene: Protein-coding gene on chromosome 5 (77,210,449 to 77,428,256, forward strand). Ensembl gene ENSG00000113231.
Subcellular location (Human Protein Atlas): Cytosol; Nucleoplasm
Pathways (Reactome):
Signal Transduction: G alpha (s) signalling events
Gene Ontology:
Molecular function: 3',5'-cyclic-AMP phosphodiesterase activity; 3',5'-cyclic-GMP phosphodiesterase activity; 3',5'-cyclic-nucleotide phosphodiesterase activity; phosphoric diester hydrolase activity
Biological process: negative regulation of cAMP/PKA signal transduction; positive regulation of ERK1 and ERK2 cascade; cAMP catabolic process; negative regulation of insulin secretion; negative regulation of insulin secretion involved in cellular response to glucose stimulus; signal transduction
Cellular component: cytosol
Genetic constraint (gnomAD): Loss-of-function variants: 17 observed, 72.58 expected, observed/expected ratio (o/e) 0.23, 90% interval 0.16 to 0.35. The upper end of that interval is the gene's LOEUF score, 0.35, which puts it in group 1 of 6, group 1 being the genes least tolerant of losing a copy. Missense variants: 678 observed, 966.38 expected, observed/expected ratio (o/e) 0.7, 90% interval 0.66 to 0.75. Synonymous variants: 372 observed, 369.71 expected, observed/expected ratio (o/e) 1.01, 90% interval 0.92 to 1.1.
Homologues: Orthologues: chimpanzee PDE8B (99% identical), macaque AGGF1 (99% identical), rat Pde8b (96% identical), pig PDE8B (96% identical), dog PDE8B (95% identical), mouse Pde8b (94% identical), guinea pig PDE8B (85% identical), tropical clawed frog pde8b (82% identical), zebrafish pde8b (66% identical), Drosophila melanogaster Pde8 (39% identical), Caenorhabditis elegans pde-6 (28% identical), Drosophila melanogaster Pde11 (14% identical), and 1 more. Paralogues in human: PDE8A (61% identical), PDE4B (18% identical), PDE11A (18% identical), PDE4A (17% identical), PDE3A (17% identical), PDE4D (17% identical), PDE3B (17% identical), PDE4C (16% identical), PDE6C (15% identical), PDE5A (15% identical), PDE1B (15% identical), PDE2A (15% identical), and 8 more.
Diseases named in the same sentence as PDE8B in open-access papers:
PDE8B is named in the same sentence as 46 diseases in open-access papers, as found by Europe PMC text mining. Sharing a sentence is not in itself a finding about the gene and the disease. The quoted sentences say what the papers report.
hypothyroidism (8 papers, 2012 to 2026). Abnormally low levels of thyroid hormone. "Among hypothyroidism-related genes, PDE8B showed a significant positive correlation (associated with increased hypothyroidism risk, β_SMR = 0.290, P_SMR = 8.33 × 10 − 8), in striking contrast to its negative correlation in hyperthyroidism (reducing risk)." (PMID 41570039, 2026). "Through integrated multi-omics analysis, this study is the first to characterize the bidirectional regulatory mechanism of PDE8B in hyperthyroidism and hypothyroidism, alongside the genetic associations of FAM227B and PDE10A with cardiovascular and neurological comorbidities." (PMID 41570039, 2026). "Interestingly, the mineralocorticoid receptor NR3C2 gene has recently been found to be up-regulated in adult-onset hypothyroidism, and PDE8B and CAPZB have been suggestively associated with hypothyroidism by GWAS." (PMID 23408906, 2013). "PDE8B exhibited bidirectional colocalization in thyroid tissue: colocalization with hypothyroidism-related signals yielded a PP4 of 0.87, and with hyperthyroidism-related signals a PP4 of 0.86, both meeting the significance criterion." (PMID 41570039, 2026). "Cross-validation by four methods identified FAM227B, PDE8B, and PDE10A as key genes for hyperthyroidism, and PDE8B as the critical gene for hypothyroidism." (PMID 41570039, 2026). "Through cross-validation of the four methods, 3 intersecting genes for hyperthyroidism (FAM227B, PDE8B, PDE10A) and 1 intersecting gene for hypothyroidism (PDE8B) were finally identified." (PMID 41570039, 2026). "Through cross-validation using four methods (SMR, TWAS, mBAT-combo, and PoPS), we identified three core candidate genes (FAM227B, PDE8B, PDE10A) associated with hyperthyroidism, with PDE8B as the sole intersecting gene showing significant association with hypothyroidism." (PMID 41570039, 2026). "For hypothyroidism, PDE8B emerged as a key potential therapeutic target." (PMID 41570039, 2026). "These agents may modulate hypothyroidism by targeting PDE8B and influencing downstream signaling pathways." (PMID 41570039, 2026). "However, SNP rs 4704397 in PDE8B has been shown to be associated with variations in serum TSH levels in several studies, and there is a well known association between hypothyroidism and recurrent miscarriage." (PMID 23237535, 2012).
adrenocortical tumors (7 papers, 2018 to 2025). "It is worth noting that variants in PDE11A and PDE8B have been found in other types of adrenocortical tumors as well." (PMID 36105398, 2022). "Out of the cAMP-specific PDEs, the one with the highest expression in the adrenal gland is PDE8B, and missense variants in PDE8B have been associated with adrenocortical tumors; the mutant forms of PDE8B have compromised ability to degrade cAMP, resulting in abnormally elevated PKA activity." (PMID 35992119, 2022). "In the present work, when the transcriptome analysis was accessed, a decrease of PDE2A, PDE5A, and PDE8A expression and a significant overexpression of PDE4B and PDE8B was observed in adrenocortical tumors, compared to normal adrenal tissue." (PMID 32098292, 2020). "A systematic genetic screening study of PDE8B variants in patients with diverse adrenocortical tumors, including PPNAD, AIMAH, secreting/non-secreting adenomas, and adrenocortical carcinomas, identified nine PDE8B variants (six of them novel)." (PMID 41511347, 2025). "However, genetic alterations in PDE11A and PDE8B have also been described in other kinds of adrenocortical tumors." (PMID 35625779, 2022). "Furthermore, in a cohort of patients with adrenocortical tumors without variants in PRKAR1A, GNAS, or PDE11A, 7 patients harbored variants in PDE8B." (PMID 36105398, 2022). "Furthermore, in a study of samples from 27 patients with adrenocortical tumors without mutations in GNAS, PRKAR1A, PDE11A, or PDE8B, abnormalities of the cAMP-signaling pathway were found, with mutation-negative ACAs having significantly decreased PDE activity." (PMID 30456751, 2018).
adenoma (4 papers, 2016 to 2025). A neoplasm arising from the epithelium. "A number of reports have identified germline PDE8B mutations in patients with adrenal hyperplasia, adenomas and carcinomas." (PMID 36313756, 2022). "Thereafter, PDE11A or PDE8B genetic variants have been found in other ACTs, including macronodular adrenocortical hyperplasias and cortisol-producing adenomas." (PMID 27625633, 2016). "Interference of cAMP/cGMP signaling pathway has been shown to be linked to tumorigenesis and PDEs overexpression has been already described in several cancer types such happened for PDE11A and PDE8B, in adrenal hyperplasia/adenomas." (PMID 37108780, 2023). "Subsequent Western blot analyses confirmed PDE8B protein overexpression in cortisol-producing adenomas compared to non-secreting adenomas." (PMID 41511347, 2025).
adrenal hyperplasia (4 papers, 2015 to 2024). "A point mutation of PDE8B was identified in patients with adrenal hyperplasia." (PMID 38355819, 2024). "Sporadic cases of micronodular adrenal hyperplasia causing ACTH-independent Cushing syndrome were also linked to mutations in phosphodiesterase-11A (PDE11A) and phosphodiesterase 8B (PDE8B)." (PMID 25775093, 2015). "Heterogeneous expression of the mutant in HEK cells increased cellular cAMP levels, suggesting that impaired PDE8B function, amongst other factors, may contribute to the development of adrenal hyperplasia." (PMID 38355819, 2024).
Cushing syndrome (4 papers, 2015 to 2026). Cushing's syndrome (CS) encompasses a group of hormonal disorders caused by prolonged and high exposure levels to glucocorticoids that can be of either endogenous (adrenal cortex production) or exogenous (iatrogenic) origin. "Mutations in PRKAR1A, PDE11A, and PDE8B have all been implicated in the pathogenesis of bilateral micronodular adrenocortical disease presenting with Cushing syndrome." (PMID 29594118, 2018). "Benign adrenal cortical tumors presenting with Cushing syndrome often have diverse mutations (PRKACA, PRKAR1A, GNAS, PDE11A, and PDE8B) involving the cyclic AMP signaling pathway." (PMID 29594118, 2018).
thyroid cancer (3 papers, 2013 to 2024). "Abnormal expression of PDE8B has been linked to various diseases and cancer pathologies, including associations with metastasis in thyroid carcinoma." (PMID 38989284, 2024).
adrenal Cushing syndrome (2 papers, 2018 to 2020). "Germline or sporadic inactivating PRKAR1A, PDE11A, and PDE8B mutations have also been described in i-PPNAD causing adrenal Cushing syndrome." (PMID 29594118, 2018). "Genome-wide associations studies demonstrate that PDE2A, PDE8B, and PDE11A modulate steroidogenesis and are associated with adrenal Cushing’s syndrome and/or bilateral adrenal hyperplasia." (PMID 32098292, 2020).
adrenocortical adenoma (2 papers, 2020 to 2022). "Alterations of PDE11A and PDE8B were not specific of PPNAD and were further described in other types of adrenocortical tumors: PBMAH, adrenocortical adenomas (ACAs), nonsecreting adrenocortical adenoma and adrenocortical carcinomas (ACCs)." (PMID 32783015, 2020).
infertile (2 papers, 2020 to 2024). "Higher frequency of the “A” allelefor PDE8B rs4704397 polymorphism in SCH relatedinfertile patients which revealed “A” as a risk allelefor infertility in IF-SCH females." (PMID 32681624, 2020). "The present study reports an association of PDE8B rs4704397 polymorphism with infertility inSCH females." (PMID 32681624, 2020). "We therefore, aimed to estimate the prevalence of SCH in infertilefemales and explore association of PDE8B rs4704397and rs6885099 polymorphisms in infertile females of Gujarat population." (PMID 32681624, 2020).
Miscarriage (2 papers, 2012 to 2020). A pregnancy that ends at a stage in which the fetus is incapable of surviving on its own, defined as the spontaneous loss of a fetus before the 22th week of pregnancy. "Earlier, PDE8B rs4704397 was also found to associatewith recurrent miscarriage." (PMID 32681624, 2020). "Bivariate associations between homozygous A/A (OR 1.57, 95% CI 0.98-2.52) as well as G/G carriers (OR 1.52, 95% CI 1.02-2.25) of SNP rs 4704397 in PDE8B and recurrent miscarriage were verified (test for trend across all 3 genotypes, p = 0.059)." (PMID 23237535, 2012). "After adjustment for known confounders such as age, BMI and smoking, the association between homozygous A/A (AOR 1.63, 95% CI 1.01 - 2.64, p = 0.045) and G/G (AOR 1.52, 95% CI 1.02 - 2.27, p = 0.039) carriers of SNP rs 4704397 in PDE8B and recurrent miscarriage remained." (PMID 23237535, 2012).
Obesity (2 papers, 2017 to 2024). Accumulation of substantial excess body fat. "This is in line with another study in 867 children with obesity, investigating the effects of variations in PDE8B on TSH concentrations, which is strongly expressed in the thyroid gland, finding these effects to be independent of BMI, but with an additive effect of BMI on TSH concentrations." (PMID 28333968, 2017).
ovarian carcinoma (2 papers, 2015 to 2022). A malignant neoplasm originating from the surface ovarian epithelium. "Downregulation of the steroidogenic regulator PDE8B, for example, explains the increased membrane fluidity in ovarian cancer cells, which has potential applications in the development of new biomarkers and treatment of ovarian cancer and deserves further investigation." (PMID 35719392, 2022). "Further, we have found that PDE8B is strongly down-regulated in ovarian cancer." (PMID 26807200, 2015). "As the PDE8B is a negative regulator of steroidogenesis, its down-regulation, is expected to drive the synthesis of steroids that are essential in supporting the growth of ovarian cancer cells." (PMID 26807200, 2015).
Parkinsonism (2 papers, 2021 to 2025). Characteristic neurologic anomaly resulting from degeneration of dopamine-generating cells in the substantia nigra, a region of the midbrain, characterized clinically by shaking, rigidity, slowness of movement and difficulty with walking and gait. "The indication that PDEs are intimately involved in the pathophysiology of different movement disorders further stems from recent discoveries that mutations in genes encoding different PDEs, including PDE2A, PDE8B, and PDE10A, are responsible for rare forms of monogenic parkinsonism and chorea." (PMID 34155691, 2021).
primary pigmented nodular adrenocortical disease (2 papers, 2020 to 2026). A form of bilateral adrenocortical hyperplasia that is often associated with adrenocorticotrophin hormone (ACTH) independent Cushing syndrome and is characterized by small to normal sized adrenal glands containing multiple small cortical pigmented nodules (less than 1 cm in diameter). "Variants in PDE8B predispose to primary pigmented nodular adrenocortical disease (PPNAD), a bilateral form of micronodular adrenal hyperplasia that causes ACTH (adrenocorticotropic hormone)-independent Cushing’s syndrome." (PMID 32098292, 2020).
thyroid (2 papers, 2021 to 2026). "The 11 selected thyroid-specific RNA transcripts (TPO, TG, GFRA2, IYD, PDE8B, WDR86, C16orf89, DGKI, DIO2, TSHR, and PAX8) were amplified from healthy volunteers and thyroid patients." (PMID 34512731, 2021).
female infertility (1 paper, 2020). Diminished or absent ability of a female to achieve conception. "Polymorphisms of phosphodiesterase 8B gene (PDE8B) have been linked with various diseases,including female infertility." (PMID 32681624, 2020).
glioblastoma (1 paper, 2024). The most malignant astrocytic tumor (WHO grade IV). "The underlying mechanisms suggest that while PDE8B expression is reduced in high-grade gliomas, it actively promotes tumor proliferation, invasion, and growth in high-grade glioblastoma cell lines, possibly due to differing cell origins in high-grade versus low-grade gliomas." (PMID 38989284, 2024).
glioma (1 paper, 2024). A benign or malignant brain and spinal cord tumor that arises from glial cells (astrocytes, oligodendrocytes, ependymal cells). "In summary, our study comprehensively investigates the origins, metabolic profiles, and clinical implications of gliomas across different grades, highlighting the significant role of the metabolism-associated enzyme PDE8B as both a biomarker and a driver of glioma progression." (PMID 38989284, 2024). "Consistent with the changes in expression, patients with higher expression of LDHA, MIF, NAMPT, PGK1, SAT1, and PLOD2, and lower expression of ALDOC, ABAT, ADCY2, GALNT13, and PDE8B showed poorer survival rates in all glioma samples." (PMID 38989284, 2024). "Our results highlight phosphodiesterase 8B (PDE8B) as a potential benign prognostic biomarker for glioma, leading us to further investigate its impact on glioma growth through cellular and animal studies." (PMID 38989284, 2024). "Further, Western blotting assay results suggested that the protein expression of PDE8B was markedly downregulated in glioma tissues compared with adjacent tissues (normal)." (PMID 38989284, 2024). "Intriguingly, we found that PDE8B is predominantly expressed in astrocytes and OPCs of glioma, as demonstrated through UMAP analysis." (PMID 38989284, 2024). "Crucially, the metabolic enzyme phosphodiesterase 8B (PDE8B) was found to be exclusively expressed and progressively downregulated in astrocytes and OPCs in higher-grade gliomas." (PMID 38989284, 2024). "This research delineates metabolic differences between glioma grades and identifies critical genes in glioma metabolism, offering new insights into glioma progression and treatment strategies, with a focus on PDE8B as a pivotal metabolic enzyme." (PMID 38989284, 2024). "This research not only advances our understanding of the complex functions of PDE8B in gliomas but also suggests new avenues for targeted therapeutic strategies." (PMID 38989284, 2024). "The expression of PDE8B decreased with increasing glioma grade." (PMID 38989284, 2024). "Moreover, RT-qPCR assay verified that the mRNA expression of PDE8B was significantly downregulated in the glioma group compared with the normal group." (PMID 38989284, 2024). "The expression of PDE8B decreased with the increase of glioma grade (II-IV)." (PMID 38989284, 2024). "Moreover, our single-cell transcriptomic analysis revealed that PDE8B expression is markedly higher in low-grade than in high-grade gliomas, a finding substantiated at the cellular and tissue levels through various methods including qPCR, Western blotting, and immunohistochemistry." (PMID 38989284, 2024). "Subsequent IHC staining revealed the expression of PDE8B, ABAT, and ADCY2 proteins in glioma WHO grades II-IV." (PMID 38989284, 2024). "Similar to the TCGA datasets, all 11 genes exhibited WHO grade-dependent expression in glioma samples, with 6 upregulated (LDHA, MIF, NAMPT, PGK1, SAT1, and PLOD2) and 5 downregulated genes (ALDOC, ABAT, ADCY2, GALNT13, and PDE8B)." (PMID 38989284, 2024). "This decreased expression identifies PDE8B as a metabolism-related oncogene in IDH-mutant glioma, marking its dual role as both a protective marker for glioma grading and prognosis and as a facilitator in glioma progression." (PMID 38989284, 2024). "The protein expression of PDE8B, ABAT, and ADCY2 decreased in glioma grade IV compared with glioma grades III and II." (PMID 38989284, 2024). "The expression of PDE8B, ABAT, and ADCY2 proteins decreased with increasing glioma WHO grade." (PMID 38989284, 2024). "Additionally, the structural and functional similarities between PDE8B and another family member, PDE8A, which has been found to regulate stemness in glioma-initiating cells and exhibit tumor-suppressive properties, further complicate the understanding of their roles in cancer." (PMID 38989284, 2024).
glioma (continued). "Similarly, aside from its established role in cAMP hydrolysis, PDE8B may engage in non-canonical activities that could elucidate its function in glioma progression." (PMID 38989284, 2024).
hyperthyroidism (1 paper, 2026). Overactivity of the thyroid gland resulting in overproduction of thyroid hormone and increased metabolic rate. "We hypothesize that the positive association signal of PDE8B may be implicated in the remodeling of hormone feedback regulatory pathways during hyperthyroidism." (PMID 41570039, 2026). "For hyperthyroidism, PDE10A and PDE8B are critical potential targets." (PMID 41570039, 2026). "These drugs may regulate hyperthyroidism-related physiological processes by acting on PDE10A and PDE8B, ameliorating disease Phenotypes." (PMID 41570039, 2026).
Insulin resistance (1 paper, 2021). Increased resistance towards insulin, that is, diminished effectiveness of insulin in reducing blood glucose levels. "It has been observed that PDE3A, PDE3B, PDE4B, PDE4D, and PDE8B in rat islets and in INS-1E cells activate multiple signal pathways critical for pancreatic beta cell function, and their abnormalities are associated with insulin resistance." (PMID 35046895, 2021).